MMRN2 (multimerin 2)
Description:
Extracellular matrix protein. Affects several essential steps in angiogenesis including endothelial cell proliferation, migration, and tube formation. Positively regulates angiogenesis by acting as a ligand for CD93 receptor.
Synonyms: EMILIN3; EndoGlyx-1; FLJ13465; EMILIN-3
Tractability: Antibody: UniProt places it where antibodies can reach, with high confidence; UniProt predicts a signal peptide or a membrane-spanning region; its Gene Ontology location is reachable by antibodies, with medium confidence.
Gene: Protein-coding gene on chromosome 10 (86,935,540 to 86,969,481, reverse strand). Ensembl gene ENSG00000173269.
Subcellular location: Secreted, extracellular space, extracellular matrix
Subcellular location (Human Protein Atlas): Vesicles; Predicted to be secreted
Pathways (Reactome):
Metabolism of proteins: O-linked glycosylation
Gene Ontology:
Molecular function: protein binding; receptor ligand activity; extracellular matrix structural constituent
Biological process: angiogenesis; negative regulation of blood vessel endothelial cell proliferation involved in sprouting angiogenesis; negative regulation of cell migration; negative regulation of cell migration involved in sprouting angiogenesis; negative regulation of cell population proliferation; negative regulation of vascular endothelial growth factor receptor signaling pathway; positive regulation of epithelial tube formation; positive regulation of morphogenesis of an epithelium; cell adhesion; cell migration involved in sprouting angiogenesis; positive regulation of defense response to bacterium; signal transduction
Cellular component: extracellular exosome; extracellular matrix; extracellular region; endoplasmic reticulum lumen; multimerin complex; non-collagenous component of interstitial matrix; basement membrane
Genetic constraint (gnomAD): Loss-of-function variants: 55 observed, 63.64 expected, observed/expected ratio (o/e) 0.86, 90% interval 0.69 to 1.08. The upper end of that interval is the gene's LOEUF score, 1.08, which puts it in group 4 of 6, group 1 being the genes least tolerant of losing a copy. Missense variants: 1,263 observed, 1,189.2 expected, observed/expected ratio (o/e) 1.06, 90% interval 1.01 to 1.11. Synonymous variants: 564 observed, 514.81 expected, observed/expected ratio (o/e) 1.1, 90% interval 1.02 to 1.17.
Homologues: Orthologues: chimpanzee MMRN2 (99% identical), macaque MMRN2 (95% identical), pig MMRN2 (73% identical), rabbit MMRN2 (68% identical), mouse Mmrn2 (66% identical), rat Mmrn2 (65% identical), dog MMRN2 (60% identical), tropical clawed frog mmrn2 (34% identical), zebrafish mmrn2a (24% identical), zebrafish mmrn2b (12% identical). Paralogues in human: MMRN1 (20% identical), EMILIN1 (15% identical), EMILIN2 (14% identical), EMILIN3 (11% identical).
Diseases named in the same sentence as MMRN2 in open-access papers:
MMRN2 is named in the same sentence as 17 diseases in open-access papers, as found by Europe PMC text mining. Sharing a sentence is not in itself a finding about the gene and the disease. The quoted sentences say what the papers report.
glioma (5 papers, 2018 to 2023). A benign or malignant brain and spinal cord tumor that arises from glial cells (astrocytes, oligodendrocytes, ependymal cells). "MMRN2 expression was upregulated in low-grade glioma and downregulated in gastric cancer, and MMRN2 expression upregulation was associated with poor clinical outcomes in low-grade glioma." (PMID 37660019, 2023). "They reported that the MMRN2 expression level is associated with WHO grade in glioma, while MMRN2 expression is low in normal brain vessels." (PMID 37660019, 2023). "And Beroukhim dataset and TCGA dataset showed that there were lower in MMRN2 expression in Brain and CNS Cancers compared to normal tissues." (PMID 32175193, 2020). "The result from Lee dataset showed that MMRN2 was over-expressed in Brain and CNS Cancers, respectively." (PMID 32175193, 2020). "We found that MMRN2 expression correlates to WHO grade in glioma, and that the level is considerably lower in normal brain vessels." (PMID 29763414, 2018). "MMRN2 was expressed in CD31-positive tumor vessels of human glioblastoma (grade IV glioma), colocalizing with CD93 expression." (PMID 29763414, 2018). "Gliomas with high vascular expression of CD93 express higher levels of MMRN2 and show enhanced fibronectin deposition." (PMID 29763414, 2018). "The interaction between CD93 and multimerin-2 (MMRN2) delivers integrin-dependent signals to regulate Src activation, fibronectin deposition, endosialin loss and prevent the development of fibrosis in ECM during glioma angiogenesis." (PMID 36006582, 2022). "CD93 and MMRN2 expression correlates with increased fibronectin deposition in human glioma vessels." (PMID 29763414, 2018). "Moreover, high CD93 expression in glioma is related to high MMRN2 expression." (PMID 37660019, 2023). "Similarly, MMRN2 was highly expressed in murine GL261 glioma vasculature, colocalizing with CD93." (PMID 29763414, 2018). "Similar to our previous observation that CD93 expression is increased in the vasculature of human high-grade glioma (HGG), MMRN2 and fibronectin were significantly elevated in WHO grade III and IV glioma compared with low-grade glioma (LGG; WHO grade II) or control brain samples." (PMID 29763414, 2018).
gastric cancer (2 papers, 2018 to 2023). A primary or metastatic malignant neoplasm involving the stomach. "Indeed the knockdown of Multimerin-2 impaired tube formation on MATRIGEL® in the presence of conditioned media from gastric cancer cells." (PMID 30544909, 2018). "We provided evidence that the expression of Multimerin-2 and EMILIN-2 are significantly altered in a number of gastric cancer patients." (PMID 30544909, 2018). "In conclusion, in this study we characterized the expression of EMILIN-1, Multimerin-2 and EMILIN-2 in the gastric normal mucosa and in gastric cancer." (PMID 30544909, 2018). "In particular, Multimerin-2 and EMILIN-2 affect angiogenesis and vascular efficiency, whereas EMILIN-1 affects lymphangiogenesis, which may also play a role in gastric cancer development representing an important route for metastatic dissemination." (PMID 30544909, 2018).
lung adenocarcinoma (2 papers, 2018 to 2021). A carcinoma that arises from the lung and is characterized by the presence of malignant glandular epithelial cells. "Mutations in three genes (DNAJC2, GMPPA, or MMRN2) are negatively associated with survival in lung adenocarcinoma." (PMID 33791386, 2021). "Mutations in GMPPA, DNAJC2, and MMRN2 were significantly associated with patient mortality in lung adenocarcinoma of Pan-Lung Cancer cohort." (PMID 30419062, 2018).
lung carcinoma (2 papers, 2018 to 2024). "A similar association between a high CD93 score and higher MMRN2 and fibronectin scoring was also observed in primary lung cancer." (PMID 38441970, 2024). "Notably, high CD93 scores in the vasculature of lung cancer metastasis were associated with higher MMRN2 and fibronectin scores in the same tumor tissue." (PMID 38441970, 2024). "CD93, MMRN2, and fibronectin expression was observed in the vasculature of primary lung cancer as well as in lung metastases and melanoma metastases." (PMID 38441970, 2024). "In LUAD of Pan-Lung Cancer cohort, mutations in DNAJC2, GMPPA, MMRN2, DRD3, and SETX were significantly associated with survival status, and those in DNAJC2, MMRN2, and SETX were significantly associated with overall survival." (PMID 30419062, 2018). "In LUAD of Pan-Lung Cancer cohort, mutations in GMPPA, DNAJC2, and MMRN2 showed significant negative associations with survival of patients while mutations in DRD3 and SETX showed significant positive association with survival." (PMID 30419062, 2018).
pancreatic cancer (2 papers, 2017 to 2024). "In pancreatic cancer, endosialin was demonstrated to bind with MMRN2, which is a unique endothelial-specific ECM protein that has been implicated in angiogenesis and tumor progression." (PMID 38164138, 2024). "CLEC14A and CD248 can bind MMRN2 simultaneously and this occurs at the interface between endothelium and pericytes in human pancreatic cancer." (PMID 28671670, 2017). "Endosialin and CLEC14A, which is another C-type lectin domain-containing group 14 family member, could simultaneously bind with MMRN2 at the interface between the endothelium and pericytes in human pancreatic cancer and were speculated to promote tumor angiogenesis." (PMID 38164138, 2024).
anaplastic astrocytoma (1 paper, 2020). "However, the expression of MMRN2 was not markedly higher in anaplastic astrocytoma compared to normal brain tissue." (PMID 32175193, 2020).
gastric tumor (1 paper, 2019). "We found a striking loss of Multimerin-2 expression in many gastric tumor associated vessels." (PMID 31263680, 2019).
melanoma (1 paper, 2024). A malignant, usually aggressive tumor composed of atypical, neoplastic melanocytes. "We scored the fraction of blood vessels that expressed CD93 and its partners MMRN2 and fibronectin in tissue microarrays (TMAs) containing tumor tissue cores from primary and metastatic lung tumors as well as melanoma metastases." (PMID 38441970, 2024).
metastatic tumors (1 paper, 2024). "CD93, MMRN2, and fibronectin are coexpressed in the vasculature of primary metastatic tumors and metastatic lesions." (PMID 38441970, 2024).
tumor (30 papers, 2016 to 2025). "CD93 and CLEC14A have overlapping binding sites in MMRN2, and appear to elicit similar responses in tumor vasculature upon deficiency." (PMID 38441970, 2024). "Multimerin 2 (MMRN2) has anti-angiogenesis effects, and its down-modulation occurs in the context of tumor-associated angiogenesis." (PMID 28635679, 2017). "Multimerin-2 (MMRN2) is a unique endothelial specific extracellular matrix protein that has been implicated in angiogenesis and tumour progression." (PMID 28671670, 2017). "To assess the role of MMRN2 and its active deletion mutant in tumor-associated angiogenesis, we employed HT1080 cells since the two molecules did not affect their proliferation or their apoptotic rate." (PMID 26655500, 2016). "Indeed, tumor-bearing mice over-expressing multimerin-2 showed impaired vascularization and reduced tumor growth, and, on the other hand, multimerin-2 expression was lower in tumor-associated vessels in GC patients with respect to the normal mucosa counterpart." (PMID 32456248, 2020). "In vitro and in vivo assays utilizing specific clone C4, inhibition of CLEC14a-MMRN2 interaction led to inhibition of tube formation, sprouting angiogenesis, and slowed subcutaneous tumor growth." (PMID 38468017, 2024). "Third, the expression levels of CD93, IGFBP7, and MMRN2 in various solid tumors and their relationship with the clinical characteristics of tumor patients should be further investigated." (PMID 37660019, 2023). "CLEC14A is a tumour endothelial marker, it induces sprouting angiogenesis by directly binds to with MMRN2." (PMID 33761933, 2021). "In this study, we developed a novel angiogenesis score and feature genes (MMRN2, CLEC14A, ACVRL1, EFNB2, and TEK) which was associated with tumor angiogenesis microenvironment and prognosis in KIRC patients." (PMID 33761933, 2021). "Multimerin-2 (MMRN2) is an endothelial selective extracellular matrix protein implicated in angiogenesis and tumor progression." (PMID 30847027, 2019). "Since MMRN2 and fibronectin were heterogeneously expressed in tumor vessels, a semiquantitative scoring method was used based on the proportion of positive vessels in each core." (PMID 29763414, 2018). "Taken together, our data support a key role of CD93 and MMRN2 in fibronectin fibrillogenesis, which is crucial for tumor angiogenesis and vascular integrity." (PMID 29763414, 2018). "Above all, we have uncovered a novel CD93/MMRN2/β1 integrin/fibronectin signaling axis that orchestrates tumor angiogenesis and vascular stability in cancer." (PMID 29763414, 2018). "MMRN2 was previously found to be upregulated in tumor vessels in experimental cancer models, and to bind to CLEC14A." (PMID 29763414, 2018). "Accordingly, both the in vivo analyses and the examinations of the tumor sections indicated that the over-expression of MMRN2 and the Δ2 deletion mutant halted the development of tumor associated vessels." (PMID 26655500, 2016). "In this study, blocking MMRN2 interaction with ligands, namely CLEC14a, in vitro and in vivo, resulted in angiostatic effect and reduced tumor implant volume, implying that binding MMRN2 with its ligand results in natively proangiogenic signaling, an understanding that is currently debated." (PMID 38468017, 2024). "We showed that CD93 mainly played roles in the tumor-associated vasculature, MMRN2 mainly played roles in the quiescent vasculature, and IGFBP7 could play roles in both the quiescent and tumor-associated tumors vasculature." (PMID 37660019, 2023). "MMRN2 might act as a homeostatic barrier to inhibit EC migration, angiogenesis, and tumor growth, promote vascular maturation, and maintain vascular stability." (PMID 37660019, 2023). "MMP-9 mediates MMRN2 degradation and enhances tumor angiogenesis." (PMID 36906534, 2023). "MMRN2, an extracellular matrix molecule specifically secreted by endothelial cells, played an important role in the regulation of endothelial cell function, neo-angiogenesis and tumor progression." (PMID 32175193, 2020).
tumor (continued). "However, it is important to note that this dual‐targeting MMRN2 fragment Fc fusion protein was expressed directly in the tumour microenvironment by genetically engineered tumour cells." (PMID 31287944, 2019). "In this setting, CD248 binding to its ligands that are upregulated in tumour angiogenesis (i.e. MMRN2 or fibronectin etc.)may inhibit T‐cell proliferation." (PMID 31287944, 2019). "To determine whether the observed interaction between CD93 and MMRN2 is likely to occur in tumor vessels, we examined the expression pattern of MMRN2 in tumors." (PMID 29763414, 2018). "CD93 and MMRN2 interact in human endothelial cells and colocalize in tumor vessels." (PMID 29763414, 2018). "Our study shows that MMRN2 is a key interaction partner of CD93 during tumor angiogenesis." (PMID 29763414, 2018). "Some in vitro and in vivo studies suggested that multimerin 2 may reduce tumour angiogenesis and growth by interfering with the vascular endothelial growth factor (VEGF-A/VEGFR2) pathway thus making it a potential candidate in developing cancer treatment." (PMID 28522939, 2017). "This MMRN2 peptide is anti-angiogenic in vitro and reduces tumour growth in mouse models." (PMID 28671670, 2017). "Therefore, MMRN2 expression might influence the function of the tumor vasculature and, in turn, influence its effect on cancer therapy." (PMID 37660019, 2023). "However, MMRN2 expression was positively correlated with tumor grades in LGG." (PMID 32175193, 2020). "Thus, MMRN2 may bind many cytokines impinging on angiogenesis and affecting the tumor microenvironment through different mechanisms." (PMID 26655500, 2016). "Given that expression of MMRN2 is altered in a number of tumor types, it is conceivable that the growth of the tumors as well as the therapeutic efficacy may be significantly affected depending on the levels of MMRN2 expression." (PMID 26655500, 2016). "As a tumor vascular marker, TEM1 interacts ECM proteins (e.g., multimerin-2 and fibronectin) and mediates cell adhesion and migration to support tumor progression and invasion 19-21, and these functions have diagnostic and therapeutic importance." (PMID 39113704, 2024). "CD93 and MMRN2 are both up-regulated in tumor vasculature during tumor progression, suggesting that the CD93–MMRN2 interaction regulates tumor angiogenesis." (PMID 36353214, 2022). "For example, MMRN2’s interaction with CD93 activates β1 integrin signalling, which leads to fibronectin fibrillogenesis and tumour angiogenesis." (PMID 35132992, 2022). "Previous studies have reported that MMRN2 and CD93 colocalize in neoplastic tissues of different origins and are highly expressed during tumor angiogenesis, which is consistent with the fact that this molecule is deposited along blood vessels." (PMID 36106120, 2022). "The interaction between the MMRN2 coiled-coil region and CLEC14A and CD93 plays a role in tumour angiogenesis." (PMID 35132992, 2022). "MMRN2 is an endothelial-specific member of the EMI domain endowed (EDEN) protein family and the component of the ECM; it is consistently deposited along tumor capillaries and is related to neovascularization in neoplastic tissues." (PMID 36106120, 2022). "The MMRN2 gene located on 10q22 interacts with the VEGF pathway to promote angiogenesis and hence tumor growth." (PMID 34178034, 2021). "A recombinant peptide of MMRN2 that blocks CLEC14A binding to endothelial is anti-angiogenic in vitro and in mice slows tumor growth." (PMID 30847027, 2019). "As adhesion molecule, CD93 contributes to EC adhesion and migration through its interaction with Multimerin-2 (MMRN2), an endothelial-specific member of the EDEN family, consistently deposited in the extracellular environment of tumor vasculature." (PMID 31138217, 2019).
tumor (continued). "In particular, we analyzed the expression of Multimerin-2 a glycoprotein expressed by endothelial cells displaying angiostatic functions and EMILIN-2, known to affect tumor growth both directly and indirectly impinging on angiogenesis." (PMID 30544909, 2018). "The authors do recognize that studies have shown MMRN2 to impair VEGFR-2 signaling, which may have important implications in tumor models." (PMID 38468017, 2024). "Nonetheless, normalization of tumor vasculature has been found to promote a host of favorable alterations to the TME, as we have recently demonstrated in preclinical murine models by disrupting CD93 interaction with IGFBP7/MMRN2." (PMID 38468017, 2024). "Multimerin-2 (MMRN2), an endothelial extracellular matrix protein, is angiostatic by virtue of interfering with VEGF/VEGFR2 signaling, regulation of which occurs during tumor angiogenesis; it is also involved in cell–cell junctional stability." (PMID 35614104, 2022). "Also, recent studies have confirmed that the appearance of Multimerin-2 and EMILIN-2 is significantly altered in gastric cancer patients and EMILIN2 has a bidirectional role in tumor micro environments." (PMID 32175193, 2020).
GI tumors (1 paper, 2020). "Multimerin-2 is highly expressed along the blood vessels in the normal gastric and colonic mucosa whereas in many GI tumor-associated vessels the expression of the molecule is significantly altered." (PMID 32456248, 2020). "Multimerin-2 and Elastin microfibril interfacer 2 (EMILIN-2) are two ECM proteins, both belonging to the EMI domain endowed (EDEN) family, that display key functions in angiogenesis and have been extensively studied in the context of GI tumors." (PMID 32456248, 2020).
MMRN2 also shares sentences with these, for which no sentence is quoted: cancer (3 papers); glioblastoma (1); invasive breast carcinoma (1); lung squamous cell carcinoma (1); myocardial infarction (1); small cell lung carcinoma (1).